BRCA1 (BRCA1 DNA repair associated)
Diseases named in the same sentence as BRCA1 in open-access papers (continued):
Sharing a sentence is not in itself a finding about the gene and the disease.
cancer (continued). "Therefore, the "basal-like" types are over-represented in the 12 nonBRCA1-mutant samples which are classified as BRCA1-mutant cancers by TST, arguing for the biological relevance of the top-scoring triplet." (PMID 19695104, 2009). "We also estimated the overall mortality in the absence of any cancer for BRCA1 and BRCA2 mutation carriers separately." (PMID 19277124, 2009). "Unlike other tumor suppressor genes, loss or mutation of BRCA1 confers a selective risk for cancer development in organs such as breast, ovary and prostate." (PMID 20046879, 2009). "This sequence may enhance the proposed role of BRCA1 in regulating ERα expression in BRCA1 and basal like cancers." (PMID 19724277, 2009). "However, when BRCA1 cancers were assessed as a separate group, cytoplasmic FIH correlated with shorter relapse-free (P=0.007) and overall survival (P=0.026)." (PMID 19724277, 2009). "However, little is known about the role of HIF-1α in hereditary breast carcinogenesis with only one report in a small series (n=30) suggesting overexpression of HIF-1α present in a higher frequency in BRCA1-related cancers than sporadic cancers." (PMID 19724277, 2009). "Basal-like tumours are more frequently observed in patients with BRCA1-related cancers." (PMID 19165203, 2009). "However, BRCA1 methylation only accounted for 7/52 (13.5%) of those sporadic carcinomas with low or intermediate BRCA1 expression." (PMID 19602291, 2009). "Increased expression of miR-29a and miR-29b was seen in the combined group of carcinomas with any demonstrable BRCA1/2 loss compared to the group with no demonstrable BRCA1/2 abnormalities." (PMID 19798417, 2009). "All BRCA1 and BRCA2 pathogenic mutations resulted in gene expression changes relating to cell cycle, cancer and cellular growth and development, while BRCA1 and BRCA2 missense mutations shared some additional similarities (cell death and cell development pathways)." (PMID 18497862, 2008). "Serially transplanted tumors and cell lines derived from these tumors recapitulate the gene expression pattern of the tumor of origin and provide potentially useful tool for preclinical studies in vitro and in vivo, and studies of Brca1-associted cancer stem cells." (PMID 18394172, 2008). "Incorporation of these additional cancer phenotypes into the model should provide greater discrimination between BRCA1 and BRCA2 mutation carriers and noncarriers." (PMID 18349832, 2008). "Although above studies suggested that both ERCC1 and BRCA1 may serve as effective biomarkers for chemosensitivity in cancer patients with primary tumor, the information on these biomarkers is still limited in metastases." (PMID 18402708, 2008). "Interestingly, decreased PTEN mRNA levels observed in cancers with BRCA1 mutations and increased PI3KCA copy number in cancers with epigenetic loss of BRCA1 were almost mutually exclusive." (PMID 18208621, 2008). "BRCA1 expression confers differential chemosensitivity in cancer cell lines." (PMID 19002265, 2008). "The existence of cancer stem cells associated with BRCA1 mutations or downregulation has not been reported." (PMID 18241344, 2008). "The products of two tumour suppressor genes, BRCA1 and WRN, have roles in decatenation checkpoint function, and mutations in either gene may increase the likelihood of cancer in part because of the checkpoint deficiency." (PMID 17211475, 2007). "DNA repair capacity of peripheral blood lymphocytes from 25 cancer-free female heterozygous BRCA1 mutation carriers and 25 non-carrier controls was assessed at baseline and following cell exposure to γ – irradiation (2 Gy)." (PMID 17213827, 2007).
cancer (continued). "Participants consisted of 339 Australian Ashkenazi Jewish women who provided a blood sample for research used to test for Ashkenazi Jewish ancestral mutations in the genes BRCA1 and BRCA2, and were offered their genetic test result through a cancer genetics service." (PMID 17102813, 2006). "The risk factors for BRCA1 and BRCA2 cancers appear to be different." (PMID 16563180, 2006). "Four cases were known BRCA1 mutation carriers and two cases belonged to untested families and have chosen to not undergo testing themselves after their cancer diagnoses." (PMID 15756256, 2005). "Variation in the penetrance estimates for BRCA1 and BRCA2 mutation carriers suggests that other genetic polymorphisms may modify the cancer risk in carriers." (PMID 15138485, 2004). "Furthermore, high expression of BRCA1 in pachytene spermatids correlates with a significant down regulation of at least one cancer testis antigen, MAGE-B4." (PMID 15383145, 2004). "This group comprises of individuals from families with a known BRCA1/2 mutation that have not inherited the mutation predisposing them to increased risk of developing cancer and for whom the main outcomes are psychological." (PMID 15138471, 2004). "This pattern of expression was observed when the BRCA1-associated samples were compared to all sporadic cancers regardless of their expression profile characterization as BRCA1- or BRCA2-like." (PMID 15383145, 2004). "The study aims to document any psychological morbidity related to genetic testing, ascertain cancer risk perceptions and examine the ongoing risk management in BRCA1/2 carriers and noncarriers in the year following genetic testing." (PMID 15505627, 2004). "Our results suggest that carriers of a BRCA1 germline mutation have a substantial higher risk of occult carcinomas compared to BRCA2 carriers or non-informative test results." (PMID 15083174, 2004). "We then studied the effect of Tax on BRCA1-defective and BRCA1-competent cancer cells." (PMID 12698198, 2003). "Variation in the penetrance estimates for BRCA1 and BRCA2 mutations carriers suggests that other genetic polymorphisms may modify the cancer risk in carriers." (PMID 11437399, 2001). "A group of 39 patients aged under 36 years and for whom the search for Brca1 gene mutations was negative, and a group of 36 cases of sporadic cancers without data on their Brca status were used as controls." (PMID 11044356, 2000). "In contrast, the rate of bcl-2 -positive tumours was lower (31%) in Brca1 -carcinomas than in carcinomas without Brca1 mutation (90%) (P< 10(-3))." (PMID 11044356, 2000). "PARPi resistance in HRD cancer cells can occur through a myriad of mechanisms, including restoration of homologous recombination (HR), DNA replication fork protection, diminished PARP trapping, PARPi efflux, chromatin remodelling, and, in the case of BRCA1-mutated cancers, 53BP1 mutation." (PMID 41495903, 2026). "Patients were categorised based on germline classification as BRCA1 positive (N = 27), BRCA2 positive (N = 21), and BRCA1/2 negative (N = 232), excluding those with BRCA1/2 variants of uncertain significance (N = 8) and pathogenic or only uncertain variants in other cancer genes (N = 62)." (PMID 41797047, 2026). "Notably, the researchers identified hundreds of variants in two cancer patients’ germline genomes within known cancer-related genes detectable only through long-read sequencing, including an intronic SV in BRCA1 that was not detectable using short-reads." (PMID 40113261, 2025).
cancer (continued). "Moreover, potential germline BRCA1/2 variants with high VAF and a frequency of 2 or higher were extracted from 3220 CGP tests performed in the northeast region, constituting the regional cancer cohort." (PMID 40249378, 2025). "The decreased BRCA1 and BRCA2 expression in this cell line are mainly due to its aggressive phenotype and defective DNA repair mechanism, which ultimately contribute to genomic instability, an important hallmark of cancer progression and therapeutic resistance." (PMID 40661795, 2025). "Therefore, men with pathogenic BRCA1 variants are not characterized by a high incidence of cancer and therefore have a higher chance of survival." (PMID 40249378, 2025). "This, coupled with mixed reports of PARPi efficacy in trials in other cancer backgrounds of HR-deficiency, led us to examine whether loss of the lysine methyltransferase and pro-NHEJ factor SETD1A influenced PARPi efficacy outside BRCA1." (PMID 39994444, 2025). "However, in BRCA1 carriers, mammography has limited added sensitivity for detecting cancers." (PMID 41083355, 2025). "Indeed, such cancers are over-represented among BRCA1 and BRCA2 carriers." (PMID 40338860, 2025). "The seminal discovery of the ability of early PARP small molecule inhibitors, or PARP1 silencing, to selectively kill BRCA1- or BRCA2-deficient cells, kickstarted the development of clinically approved PARPi, which have shown significant efficacy as monotherapy in HRR-deficient cancers." (PMID 41459749, 2025). "Thus, we conducted KEGG pathway analysis with 1162 genes that had combined binding of H3K4me3, ERα, and Flag-Brca1, and the data revealed that the five well-known oncogenic pathways, including the cancer, PI3K-AKT, Ras, MAPK, and Rap1 pathways, were among the top 10 enriched pathways." (PMID 40157910, 2025). "Importantly, genetic and pharmacological destruction of GSK3B-mediated T334 phosphorylation leads to HR repair deficiency and makes cancer cells susceptible to synthetic lethality of PARPi therapy independent of BRCA1 status." (PMID 41243969, 2025). "Additionally, patients with these mutations tended to present with more advanced stages of disease compared to those without pathogenic mutations in the BRCA1/2 genes, who exhibited a less aggressive cancer." (PMID 41463058, 2025). "Importantly, while BRCA1-mutated, BRCA2-mutated, and WT triple-negative tumors showed high rates of pCR, the frequency of NACT failure (i.e., RCB III) was similar between HR+ BRCA2-associated and WT cancers." (PMID 40547808, 2025). "The increased incidence of double-stranded DNA damage observed in both biopsies and PDGOs from BRCA1 and BRCA2 carriers is particularly concerning, as this type of damage is the most severe form of DNA damage and thought to be a general risk factor for cancer development." (PMID 41256354, 2025). "Consequently, the loss of both BRCA1 and NBR2 genes could increase the risk of cancer development and impact the clinical follow‐up." (PMID 39783935, 2025). "Thus, OFD1 depletion mimics BRCA1 deficiency and may serve as a potential therapeutic strategy to sensitize HRR-proficient cancers to PARP inhibition." (PMID 40764600, 2025). "Given that 17q loss is one of the most common events in cancer, it is not clear from the article whether any of the ‘somatic’ cases represents a true targeted BRCA1 abnormality." (PMID 40046829, 2025).
cancer (continued). "Some sporadic cancers are also characterized by HR deficiency but without BRCA1-2 mutations." (PMID 40616061, 2025). "For example, although PARP inhibitors represent a revolutionary advancement in precision medicine, their efficacy in people with germline BRCA1/2 cancer risk alleles with non-BRCA-associated cancer types may be limited." (PMID 40759574, 2025). "In the UK Biobank, 0.33% (n = 841/256,591) of women with a pathogenic variant in BRCA1/2, 70% reported no first‐degree relatives with the associated cancers, indicating that testing based on family history criteria alone fails to detect a substantial number of carriers." (PMID 40747594, 2025). "Thus, it may be expected that there is a decrease in HIF-1 protein levels as well as a lowering of global histone/DNA methylation in BRCA1-expressing cancer cells." (PMID 40863152, 2025). "Our KEGG enrichment analysis based on metabolomics data indicated that the high-expression cohort of BRCA1 was notably involved in pathways such as Protein digestion and absorption, Cysteine and methionine metabolism, D-Amino acid metabolism, and Central carbon metabolism in cancer." (PMID 41430564, 2025). "BRCA1 P/LP variants were identified in two patients (0.27%), one with a diffuse GC at 43 years and no family history of cancer and another with an unknown histology GC at 66 years and GC family history." (PMID 40446793, 2025). "Given the growing need for validated, culturally sensitive measures of cancer worry among BRCA1/2 carriers, this study aimed to translate, culturally adapt, and pilot-test the German version of the full 8-item CWS in a sample of BRCA1/2 pathogenic variant carriers in Austria." (PMID 40390061, 2025). "Additionally, POLB could be a potential target for cancer cells that are deficient MMR and BRCA1/2 to promotes synthetic lethality." (PMID 41568291, 2025). "Another key distinction between BRCA1 and BRCA2 in terms of cell cycle protein expression involves type D cyclins (D1, D3), their associated CDK such as CDK4, and the CDKIs p16, p21, and p27, which showed a lower expression in BRCA1 compared to BRCA2 carcinomas." (PMID 40136510, 2025). "Strikingly, carboplatin did not improve pCR rates in BRCA1- or BRCA2-associated carcinomas." (PMID 40547808, 2025). "When the BRCA1 protein is absent or non-functioning due to mutations, cellular integrity is compromised, rendering cells more vulnerable to chromosomal rearrangements and mutations that have the potential to induce cancer." (PMID 38542081, 2024). "In addition, other mechanisms of PARPi resistance involve modifications of the drug target, i.e., PARP1 conformation change to avoid PARP1 trapping—a phenomenon mentioned previously caused by PARPi drugs, although at present this has only been reported in pre-clinical BRCA1 mutant cancer models." (PMID 39119040, 2024). "For example, the founder mutation BRCA1 c.5470_5477del is specifically harbored by the North Han in our study (0.44% in healthy individuals and 5.89% in cancer patients), and this variant has not been reported in previous BRCA variant screening studies conducted in the south region of China." (PMID 38566028, 2024). "In addition, BRCA1 has been implicated in DNA2 recruitment to double-stranded DNA breaks, suggesting that BRCA1-deficent cancer cells might have lower levels of DNA2 localized to stalled and/or reversed replication intermediates." (PMID 38943334, 2024). "However, to the best of our knowledge there is no prospective data about BRCA1 mutation carriers or the correlation between blood iodine level and cancer risk." (PMID 38892720, 2024). "Besides the influence of inherited mutations on the incidence of cancer, women with a pathogenic BRCA1 mutation have various non-genetic modifiable factors." (PMID 39061909, 2024). "However, a substantial proportion of cancers without BRCA1/2 mutations can also manifest somatic mutational HRD molecular features, indicating the existence of other mechanisms of HRD." (PMID 39055334, 2024).
cancer (continued). "Second, the TCR database does not include personal-level data of patients with cancer, so we lacked some information including family history, social history, BRCA1/BRCA2 mutations, comorbidities, and personal history of cancer, which are factors known to affect MBC incidence." (PMID 38275884, 2024). "NANAC has not been studied in cancer, nor has it been linked to BRCA1 in any studies." (PMID 38993666, 2024). "Furthermore, BCAC and Cancer Risks Estimates Related to Susceptibility Consortium (CARRIERS), suggested BRCA1, BRCA2, ATM, PALB2, and CHEK2 genes as highly penetrant; both consortiums pinpointed that 10% of BC patients have cancer susceptibility germline mutation." (PMID 38890714, 2024). "For the patients with single primary cancer, among 542 evaluable patients (those with both germline and somatic mutations which were in same or different genes), 25 patients (4.6%) had biallelic events, and the involved genes included ATM, BRCA1, BRCA2, BRIP1, and ERCC5." (PMID 37885353, 2024). "Notably, male BRCA2 PVs carriers are significantly more likely to develop cancer, particularly BC, and are at increased risk of developing second breast and non-breast tumors, compared to male BRCA1 PVs carriers." (PMID 38339330, 2024). "For example, the identification of BRCA1 and BRCA2 mutations in breast cancer, mutL homolog 1, mutS homolog 6, and mutS homolog 6 mutations in colon cancer, and the RB1 mutation in retinoblastoma is useful for understanding cancer progression in relation to different prognoses and treatments." (PMID 39767566, 2024). "Defects in these BRCA1/2 functions may also contribute to genomic instability in cancer cells." (PMID 39007266, 2024). "Taken together, while these findings strongly indicate that the risk of tumor-directed influence on WBC BRCA1 methylation in patients diagnosed with cancer is low, in theory, such secondary effects may not be excluded." (PMID 40225940, 2024). "However, a substantial fraction of cancer patients carrying BRCA1/2 mutations do not respond to PARPis, and most patients develop resistance to PARPis over time, highlighting a major obstacle to PARPi therapy in the clinic." (PMID 39007266, 2024). "Bilateral RRM in BRCA1/2 PV carriers without previous cancer (previvors) results in a large reduction in BC risk and may confer a survival benefit in BRCA1 PV carriers." (PMID 39446752, 2024). "In addition, the clinical relevance of targeting the fork recovery mechanism in BRCA1-deficient cancers has not been explored." (PMID 38943334, 2024). "BRCA1 deficiency activates S100A9-CXCL12 signaling for cancer progression and triggers the expansion and accumulation of myeloid-derived suppressor cells, creating a tumor-permissive microenvironment and rendering cancers insensitive to immune checkpoint inhibitors." (PMID 39830522, 2024). "Consequently, it was proposed that the aberrant formation and repair of single-stranded DNA (ssDNA) gaps were the key factors underpinning the vulnerability of cancer cells to PARPi12, as BRCA1/2 proteins were shown to have a critical role in replication gap suppression (RGS)." (PMID 39191785, 2024). "Alterations in BRCA1/2 were significantly more common in uLMS compared with non-uLMS, and LMS patients with BRCA1/2 loss trended towards a more poorly differentiated histologic subtype as well as an increased mitotic count, highlighting the connection between HR and cancer predisposition." (PMID 38994959, 2024). "Consequently, PARP1 inhibition induces synthetic lethality in BRCA1/2-mutant cancer cells." (PMID 39318358, 2024).